P2RX7 (purinergic receptor P2X 7)
Diseases named in the same sentence as P2RX7 in open-access papers (continued):
Sharing a sentence is not in itself a finding about the gene and the disease.
gout (6 papers, 2014 to 2023). A condition characterized by painful swelling of the joints, which is caused by deposition of urate crystals. "In another example, comparing Sprague–Dawley Uox (uricase) knockout rats with acute gouty arthritis to those without this disease identified a mutated locus (1016) in the 5′ untranslated region of that P2rx7 gene that was associated with gout development." (PMID 37175933, 2023). "Various genetic variations in the P2RX7 gene, coding for the P2X7 receptor implicated in inflammasome activation and probably a key regulator of IL-1β production by MSU crystals during acute gout flares, have been reported to be associated with gout: rs1653624, rs7958316, rs17525809, and rs3751142." (PMID 33926105, 2021).
heart failure (6 papers, 2015 to 2023). Inability of the heart to pump blood at an adequate rate to meet tissue metabolic requirements. "The cardiac improvement observed when P2RX7 was blocked is also of clinical importance because, with prolonged patient survival (due to advances in general care), heart failure becomes a more common cause of death in DMD." (PMID 26461208, 2015).
Insulin resistance (6 papers, 2017 to 2025). Increased resistance towards insulin, that is, diminished effectiveness of insulin in reducing blood glucose levels. "Taken together, these data suggest that P2rx7 may play only a minor role if any in insulin resistance caused by overnutrition in mouse models." (PMID 33025427, 2020).
liver fibrosis (6 papers, 2015 to 2021). "P2RX7 inhibition resulted in significant protection from inflammation and fibrosis in a chemically-induced primate (non-human) liver fibrosis model." (PMID 32492075, 2020). "Inhibition of P2RX7 yielded anti-inflammatory and anti-fibrotic effects in a CCl4-induced liver fibrosis model in non-human primates." (PMID 32492075, 2020). "Consequently, in a chemically-induced nonhuman primate model of liver fibrosis, treatment with a P2RX7 inhibitor improved histological characteristics of NASH, protecting from liver inflammation and fibrosis." (PMID 32492075, 2020).
muscular dystrophy (6 papers, 2018 to 2023). Muscular dystrophy (MD) refers to a group of more than 30 genetic diseases characterized by progressive weakness and degeneration of the skeletal muscles that control movement. "Indeed, despite its limitations, BBG has been used widely to block P2RX7 in various pathologies such as neuroexcitotoxicity, graft-vs.-host disease and muscular dystrophy." (PMID 30003075, 2018).
myocardial infarction (6 papers, 2016 to 2023). Gross necrosis of the myocardium, as a result of interruption of the blood supply to the area, as in coronary thrombosis. "None of the SNPs (A1513C, rs208294, and rs3751143) for the P2RX7 gene was associated with mortality in patients with heart failure, a common consequence of myocardial infarction." (PMID 33995071, 2021).
Type I diabetes (6 papers, 2011 to 2021). "P2RX7 is a purinergic ATP-binding calcium channel expressed in microglial cells and considered a candidate gene in type I diabetes." (PMID 24967385, 2014).
cervical cancer (5 papers, 2016 to 2026). A primary or metastatic malignant neoplasm involving the cervix. "The study aims to investigate if polymorphisms in the P2RX7 gene are associated with the risk of cervical cancer in Taiwanese women." (PMID 27779103, 2016).
Dyskinesia (5 papers, 2018 to 2025). A movement disorder which consists of effects including diminished voluntary movements and the presence of involuntary movements. "Consequently, blocking P2RX7 in hemiparkinsonian rats reduced dopamine-induced dyskinesia and motor incoordination." (PMID 40948939, 2025).
influenza (5 papers, 2017 to 2023). An acute viral infection of the respiratory tract, occurring in isolated cases, in epidemics, or in pandemics; it is caused by serologically different strains of viruses (influenzaviruses) designated A, B, and C, has a 3-day incubation period, and usually lasts for 3 to 10 days. "Expression of P2RX7 following influenza stimulation was lower among older adults." (PMID 35822051, 2021).
metastatic disease (5 papers, 2013 to 2023). "We do not observe inverse correlation with the expression of previously identified miR-150 targets P2RX7 or EGR2 in our primary/metastatic tumor data." (PMID 23554878, 2013).
tauopathy (5 papers, 2019 to 2025). Neurodegenerative disorders involving deposition of abnormal tau protein isoforms (tau proteins) in neurons and glial cells in the brain. "Given that microglia highly express the P2rx7 geneand expand their population under tauopathy, we investigated microglia-specific gene signatures under P2rx7 deficiency in PS19 mice." (PMID 40678243, 2025). "Together, these findings underscore the role of P2RX7 in promoting the spread of pathological molecules via EVs in tauopathy mice and suggest that its deficiency attenuate pro-inflammatory microglial activation." (PMID 40678243, 2025). "Of note, this study focused on the effects of P2rx7 deficiency within the CNS, and whether peripheral immune cells also contribute to the observed effects in tauopathy remains to be explored." (PMID 40678243, 2025). "We detected a P2RX7-dependent increase in the number of EVs containing tau and mitochondrial molecules, which triggered a microglial inflammatory response in tauopathy model mice after intracranial injection in vivo." (PMID 40678243, 2025). "Here, using scRNA-seq, we show that P2rx7 is predominantly expressed in microglia and drives inflammatory response in a tauopathy mouse model." (PMID 40678243, 2025). "Targeting the microglial P2RX7-EV axis provides a protective mechanism against the progression of tauopathy-related neurodegenerative processes." (PMID 40678243, 2025). "To determine how P2rx7 disruption affects the microglial response to tauopathy, we performed subclustering analysis of microglia." (PMID 40678243, 2025). "The purpose of the study is to examine the therapeutic effect of an orally applicable, CNS-penetrant P2RX7 specific inhibitor on the early disease stage of a tauopathy mouse model." (PMID 32811520, 2020). "In summary, these findings demonstrate that P2rx7 deficiency in PS19 mice restores mitochondrial homeostasis and suppresses microglial inflammatory changes, EV secretion, and tauopathy phenotypes, highlighting the critical role of P2RX7 in mediating tauopathy-related disease phenotypes." (PMID 40678243, 2025). "Remarkably, P2rx7 disruption in tauopathy model mice not only reduced the expression of oxidative stress-associated genes but also decreased the conversion of microglia into the InfM state, which is characterized by the expression of Nlrp3, Il1b, and other proinflammatory cytokines." (PMID 40678243, 2025). "However, the exact mechanism by which P2RX7 contributes to the acceleration of tauopathy, neuroinflammation and neurodegeneration remains poorly understood." (PMID 40678243, 2025). "To explore whether P2rx7 disruption reduces microglial EV secretion in tauopathy, we analyzed EV-related gene expression in microglial clusters." (PMID 40678243, 2025). "Finally, whether P2RX7 directly modulates mitochondrial damage or clearance in response to tau has yet to be fully elucidated, and future studies using human-derived samples will be important to validate the relevance of the microglial response to tauopathy-associated BDEVs." (PMID 40678243, 2025). "First, although previous reports described increased P2rx7 expression in astrocytes in tauopathy, the limited effect of astrocytic P2rx7 knockout on tau propagation may reflect insufficient knockdown efficiency in our model, highlighting a potential model limitation." (PMID 40678243, 2025). "Thus, our results indicate that P2RX7 regulates EV-mediated tau and mitochondrial transfer and inflammatory activation in microglia with increased EV secretion, thereby contributing to tauopathy and neurodegeneration, highlighting the therapeutic potential of targeting the P2RX7-EV axis in AD." (PMID 40678243, 2025). "P2RX7 could be a novel therapeutic target for the early stage tauopathy development." (PMID 32811520, 2020). "Thus, P2RX7 may be a beneficial target for suppressing both Aβ accumulation and tauopathy development in AD." (PMID 32811520, 2020).
tauopathy (continued). "To investigate the role of P2rx7 in the development of tau pathology, we crossed P2rx7 knockout (P2rx7−/−) mice with a PS19 tauopathy mouse model, which overexpresses P301S mutant human tau." (PMID 40678243, 2025). "Taken together, these results suggest that P2rx7, which is highly expressed in microglia, may regulate glial mitochondrial oxidative stress in PS19 mice and that P2rx7 deficiency may reduce glial mitochondrial damage and cellular stress in the context of tauopathy." (PMID 40678243, 2025). "To investigate the molecular mechanisms of P2RX7 signaling in specific cell types involved in tauopathy, we performed scRNA-seq on brain tissues from 9.5-month-old WT, PS19, and PS19/P2rx7−/− mice via the sequential barcoding platform from Parse Biosciences." (PMID 40678243, 2025). "To test this hypothesis, we used genetic and cell type-specific disruption of P2rx7 in mouse brains and conducted multiomics-based comprehensive analysis of brain tissues and brain-derived EVs (BDEVs) from PS19 tauopathy mice." (PMID 40678243, 2025). "Our previous study revealed that treatment with GSK1482160, a CNS-penetrant P2RX7 antagonist, reduces ATP-induced secretion of EVs containing tau from microglia and misfolded tau accumulation, restoring cognitive function in a young PS19 tauopathy mouse model." (PMID 40678243, 2025). "However, the role of P2RX7 has never been examined in the context of tau spread through exosome secretion in tauopathy animal models." (PMID 32811520, 2020).
acute respiratory distress syndrome (4 papers, 2018 to 2023). Progressive and life-threatening pulmonary distress in the absence of an underlying pulmonary condition, usually following major trauma or surgery. "A comparison of P2rx7fl/fl mouse with CD4+ T (with CD4-cre)-, myeloid cells (with LySM-Cre)- or airway epithelial cell (with CCT-cre)-specific P2rx7 KO mice revealed a role for CD4+ T cell and myeloid cell P2X7 in the development of acute respiratory distress syndrome." (PMID 37175933, 2023).
dystrophinopathy (4 papers, 2015 to 2023). "In muscle, dystrophinopathy coincides with a significant P2RX7 upregulation and altered receptor signalling in muscle cells." (PMID 34101068, 2022). "The molecular mechanism leading to the P2RX7 abnormality in dystrophinopathy found both in muscle and non-muscle cells is unknown." (PMID 26461208, 2015).
endometrial cancer (4 papers, 2013 to 2025). Primary or metastatic malignant neoplasm involving the endometrium (mucous membrane that lines the endometrial cavity). "In endometrial cancer tissues and squamous cell carcinoma tissues, miR-186 served as an oncomir by suppressing targets P2RX7, FOXO1, APAF1, and RETREG1." (PMID 32195180, 2020).
Hepatitis (4 papers, 2010 to 2022). Inflammation of the liver. "However, one study, which did not link P2rx7 signaling with inflammasome activation, reported that P2rx7−/− mice were markedly protected from liver damage in ConA-induced hepatitis." (PMID 30213101, 2018).
Osteopenia (4 papers, 2018 to 2021). Osteopenia is a term to define bone density that is not normal but also not as low as osteoporosis. "Besides, depletion of demethylase TET1 and TET2 causes osteopenia phenotype in mice by impeding demethylation of P2rX7 promoter; P2rX7 deficiency further leads to MSC incapability of exosome release, which results in intracellular accumulated miR-297 targeting Runx2 signaling pathway." (PMID 32963550, 2020). "In bone marrow mesenchymal stem cells (BMMSCs), TET1 plays a key role in maintaining BMMSC and bone homeostasis by controlling exosome and miRNA release through P2X purinoceptor 7 (P2RX7) demethylation, and could be a target for the development of new therapies for osteopenia." (PMID 34656178, 2021). "To verify the role of P2rX7 on bone formation, we used P2rX7 AAV to treat osteopenia (OVX) mice." (PMID 29858571, 2018). "In vivo overexpression of P2rX7 rescues the osteopenia phenotype and BMMSC function in Tet DKO mice, suggesting that P2rX7 may be a potential therapeutic target for treating Tet-associated skeletal disorders." (PMID 29858571, 2018). "Elevating P2rX7 levels in Tet DKO mice rescued BMMSC function and osteopenia phenotype." (PMID 29858571, 2018).
Pain (4 papers, 2022 to 2025). An unpleasant sensory and emotional experience associated with actual or potential tissue damage, or described in terms of such damage. "Hence, in chronic neuropathic pain, P2RX7 can modulate T cell function through alterations in energy metabolism, while blockade of P2RX7 can ameliorate neuropathic pain." (PMID 37266437, 2023).
periodontitis (4 papers, 2018 to 2024). An acute or chronic inflammatory process that affects the tissues that surround and support the teeth. "Five hub ICD-related genes (ENTPD1, TLR4, LY96, PRF1 and P2RX7) were identified for the construction of a diagnostic model for periodontitis." (PMID 39555084, 2024). "Five key genes associated with ICD (ENTPD1, TLR4, LY96, PRF1 and P2RX7) may be diagnostic biomarkers of periodontitis and future therapeutic targets." (PMID 39555084, 2024). "In line with the findings of the validation set, our findings demonstrated that ENTPD1, TLR4, LY96, PRF1 were elevated in periodontitis patients while P2RX7 expression was decreased." (PMID 39555084, 2024). "In contrast to the healthy group, the periodontitis group had higher levels of ENTPD1, TLR4, LY96, and PRF1 expression and lower levels of P2RX7 expression, according to the qPCR data." (PMID 39555084, 2024).
retinal diseases (4 papers, 2013 to 2023). "P2RX7 antagonists including BBG may have a neuroprotective therapeutic effect in retinal diseases as well as in CNS diseases with excessive extracellular ATP." (PMID 23308196, 2013).
allergic asthma (3 papers, 2016 to 2020). A asthma with a basis in a pathological type I hypersensitivity reaction. "Although P2RX7 has already been implicated in allergic asthma, the role of P2RX4 in airway inflammation has not been elucidated yet." (PMID 27863396, 2016).
anxiety disorder (3 papers, 2023 to 2025). A category of psychiatric disorders which are characterized by anxious feelings or fear often accompanied by physical symptoms associated with anxiety. "In humans the P2RX7 gene encoding the P2X7 receptor is located at 12q24.31 chromosome position, a region already implicated in affective and anxiety disorders." (PMID 38255938, 2024).
Duchenne muscular dystrophy (3 papers, 2018 to 2020). Duchenne muscular dystrophy (DMD) is a neuromuscular disease characterized by rapidly progressive muscle weakness and wasting due to degeneration of skeletal, smooth and cardiac muscle. "Duchenne muscular dystrophy (DMD) alters P2RX7 signaling in both muscle and inflammatory cells and inhibition of this receptor resulted in a significant attenuation of muscle and non-muscle symptoms in DMDmdx mouse model." (PMID 29642926, 2018).
helminth infection (3 papers, 2018 to 2024). "With this in mind, it is highly relevant that P2rx7 signalling is also reportedly reduced in macrophages of hosts infected with S. mansoni and Trichuris suis, perhaps indicating a common mechanism of immune modulation during helminth infection." (PMID 39344634, 2024).
Hepatic steatosis (3 papers, 2017 to 2020). Steatosis is a term used to denote lipid accumulation within hepatocytes. "Finally, P2rx7−/− mice developed a hepatic steatosis characterized by a reduction of Acaca, Acacb, Fasn and Acox1 mRNA expression, as well as for ACC and FAS protein expression." (PMID 29018292, 2017).
liver diseases (3 papers, 2008 to 2020). "Taken collectively, these attributes have rendered P2RX7 an attractive target for liver diseases, including NASH." (PMID 32492075, 2020). "The diversity and heterogeneity of macrophages in liver diseases underscore the importance of P2RX7 and the need to better understand the roles of this receptor in liver-specific macrophage functions." (PMID 32492075, 2020).
lung adenocarcinoma (3 papers, 2020 to 2023). A carcinoma that arises from the lung and is characterized by the presence of malignant glandular epithelial cells. "Using the lung adenocarcinomas (LUAD) TCGA dataset, we analyzed the effect of P2RX7 expression levels on the recruitment of cytotoxic immune cells." (PMID 33510147, 2021).
nephritis (3 papers, 2016 to 2023). Inflammation of renal tissue. "Of note, A-438079 protected both P2rx7 KO and wild-type rats from nephrotoxic nephritis, indicating off-target effects of this P2X7 antagonist and highlighting the potential utility of P2rx7 KO animals to study the specificity of P2X7 antagonists." (PMID 37175933, 2023).
parasite infection (3 papers, 2017 to 2023). "The higher parasitemias observed in chronically infected P2rx7-/- mice compared with those of their B6 counterparts suggested that the P2X7 receptor is required for the development of acquired immunity to Pc malaria." (PMID 28859168, 2017).
pulmonary TB (3 papers, 2012 to 2021). "Unfortunately, studies on the effect of P2RX7 polymorphisms in susceptibility to pulmonary TB in humans have not yet been done either in vivo or in other ethnic groups." (PMID 22879892, 2012).
Allergic dermatitis (2 papers, 2009 to 2022). "P2RX7 in Allergic dermatitis in humans is related to up-regulation within the basal epidermal layer of inflamed skin of patients with atopic eczema." (PMID 35933451, 2022).
Brain atrophy (2 papers, 2022 to 2025). Partial or complete wasting (loss) of brain tissue that was once present. "P2rx7 deficiency in PS19 mice improved cognitive performance, preserved synaptic integrity, mitigated brain atrophy, and reduced both tau accumulation and microglial inflammatory activation." (PMID 40678243, 2025).
cardiomyopathy (2 papers, 2021 to 2025). A disease of the heart muscle or myocardium proper. "Among these six genes, the P2RX7 gene showed two complementary variants (rs208294 and rs3751143) whose union, having one or no copies of variant yielded a reduced risk of cardiomyopathy in CCS (OR = 0.10; 95% CI: 0.04–0.27; p = 2.19 × 10−6)." (PMID 40413218, 2025). "As a result, 20 studies were included (15 case-control and five cohorts), revealing several genes and variants associated with cardiomyopathy, among which, SLC28A3-rs7853758, RARG-rs2229774, P2RX7-rs208294 and P2RX7-rs3751143 variants gave the most consistent findings." (PMID 40413218, 2025). "Carrying one or no copy of the P2RX7-rs208294 and P2RX7-rs3751143 variants, is associated with a reduced risk of cardiomyopathy." (PMID 40413218, 2025).
cervical squamous cell carcinoma (2 papers, 2016 to 2021). A squamous cell carcinoma arising from the cervical epithelium. "The eight enrolled articles consisted of eight case–control studies with P2RX7 gene rs3751143 polymorphism and four cancer types (CLL in five studies, PTC in one study, HCC in one study, and cervical squamous cell carcinoma in all studies)." (PMID 33501930, 2021). "We therefore performed an association study of 507 cervical squamous cell carcinoma (CSCC) cases and 1619 controls to test whether specific P2RX7 SNPs are associated with susceptibility to CSCC." (PMID 27779103, 2016).
Chagas disease (2 papers, 2018 to 2026). A parasitic infection caused by Trypanosoma cruzi. "To date, no longitudinal human studies have directly assessed P2X7 expression or activity across the different stages of Chagas disease, nor clarified the influence of P2RX7 genetic polymorphisms on disease susceptibility or therapeutic response." (PMID 41573114, 2026).